PEDS1 (plasmanylethanolamine desaturase 1)
Description:
Plasmanylethanolamine desaturase involved in plasmalogen biogenesis in the endoplasmic reticulum membrane. Plasmalogens are glycerophospholipids with a hydrocarbon chain linked by a vinyl ether bond at the glycerol sn-1 position, and are involved in antioxidative and signaling mechanisms.
Synonyms: KUA; TMEM189; CarF
Tractability: Antibody: UniProt predicts a signal peptide or a membrane-spanning region. PROTAC: ubiquitination databases record sites on it.
Gene: Protein-coding gene on chromosome 20 (50,118,254 to 50,153,754, reverse strand). Ensembl gene ENSG00000240849.
Subcellular location: Endoplasmic reticulum membrane
Subcellular location (Human Protein Atlas): Endoplasmic reticulum
Gene Ontology:
Molecular function: plasmanylethanolamine desaturase activity; protein binding
Biological process: ether lipid biosynthetic process; fatty acid metabolic process
Cellular component: endoplasmic reticulum; endoplasmic reticulum membrane
Genetic constraint (gnomAD): Loss-of-function variants: 13 observed, 30.88 expected, observed/expected ratio (o/e) 0.42, 90% interval 0.27 to 0.67. The upper end of that interval is the gene's LOEUF score, 0.67, which puts it in group 2 of 6, group 1 being the genes least tolerant of losing a copy. Missense variants: 203 observed, 324.61 expected, observed/expected ratio (o/e) 0.63, 90% interval 0.56 to 0.7. Synonymous variants: 133 observed, 132.35 expected, observed/expected ratio (o/e) 1, 90% interval 0.87 to 1.16.
Homologues: Orthologues: chimpanzee PEDS1 (99% identical), dog PEDS1 (94% identical), pig PEDS1 (94% identical), guinea pig PEDS1 (93% identical), mouse Peds1 (93% identical), rat Ube2v1 (84% identical), macaque UBE2V1 (58% identical). Paralogues in human: UBE2V1 (13% identical), UBE2V2 (13% identical), UBE2C (9% identical), UBE2O (9% identical), UBE2T (9% identical), CDC34 (9% identical), UBE2A (8% identical), UBE2I (8% identical), UBE2K (8% identical), UBE2R2 (8% identical), UBE2B (7% identical), UBE2N (7% identical), and 12 more.
Diseases named in the same sentence as PEDS1 in open-access papers:
PEDS1 is named in the same sentence as 24 diseases in open-access papers, as found by Europe PMC text mining. Sharing a sentence is not in itself a finding about the gene and the disease. The quoted sentences say what the papers report.
breast carcinoma (2 papers, 2024 to 2026). "Additionally, plasmanylethanolamine desaturase-1 (PEDS1 or TMEM189) promotes tumorigenesis in gastric and breast cancers by inhibiting autophagosome formation and autophagy-dependent ferroptosis." (PMID 41596760, 2026).
monocytopenia (1 paper, 2024). "While HSPC emergence and erythropoiesis proceeded normally in Peds1-deficient larvae, they suffered from robust neutropenia and monocytopenia that was rescued by pharmacological inhibition of caspase-3." (PMID 39209813, 2024).
bacterial infection (1 paper, 2024). "Additionally, Peds1 deficiency also aggravated chronic skin inflammation and caused hyper-susceptibility to bacterial infection." (PMID 39209813, 2024). "Furthermore, the higher susceptibility of Peds1-deficient larvae to bacterial infection was fully rescued by pharmacological inhibition of caspase-3 and partially rescued by Csf3a-induced myelopoiesis." (PMID 39209813, 2024). "Hence, Peds1-deficient larvae were more susceptible to bacterial infection but, more importantly, exogenous plasmalogens not only alleviated this higher susceptibility of Peds1-deficient larvae, but also increased the resistance of wild-type larvae." (PMID 39209813, 2024). "Chronic skin inflammation worsened in Peds1-deficient larvae but was mitigated by exogenous plasmalogen, which also alleviated hyper-susceptibility to bacterial infection, as did pharmacological inhibition of caspase-3 and colony-stimulating factor 3-induced myelopoiesis." (PMID 39209813, 2024).
infection (1 paper, 2024). The state of being infected such as from the introduction of a foreign agent such as serum, vaccine, antigenic substance or organism. "Notably, supplementation with exogenous plasmalogen (HsVEPE1) not only mitigated the higher susceptibility of Peds1-deficient larvae to ST infection, but it also robustly increased the resistance of wild type larvae." (PMID 39209813, 2024). "As expected, supplementation with the plasmalogen precursor (HsAEPE1) increased infection resistance of control larvae but failed to alleviate the higher susceptibility to ST of Peds1-deficient larvae." (PMID 39209813, 2024).
inflammation (1 paper, 2024). Aberrant reaction of the microcirculation characterized by movement of fluid and leukocytes from the blood into extravascular tissues. "Importantly, our study reveals that Peds1 deficiency in zebrafish exacerbates both acute and chronic inflammation, hinting that the diminished plasmalogen levels observed in chronic inflammation-linked diseases might be a cause rather than a consequence of these diseases." (PMID 39209813, 2024).
neurodegenerative disease (1 paper, 2023). A disorder of the central nervous system characterized by gradual and progressive loss of neural tissue and neurologic function. "Our study supports that genetic variation in TMEM189 affects the levels of PEDS1 protein expression regulating the amount of PE(P‐18:1_18:2) in muscle, which could possibly be used as a dietary supplement to prevent or treat neurodegenerative diseases." (PMID 37013465, 2023).
PEDS1 also shares sentences with these, for which no sentence is quoted: cancer (12 papers); glioblastoma (3); tumor (3); Alzheimer disease (1); chondrosarcoma (1); connective tissue disorder (1); depression (1); Ewing sarcoma (1); gastric cancer (1); glioma (1); Hepatic steatosis (1); male infertility (1); neuroblastoma (1); neutropenia (1); Obesity (1); osteoporosis (1); Parkinson disease (1); type II diabetes (1).